BCL2L1 (BCL2 like 1)
Description:
Potent inhibitor of cell death. Inhibits activation of caspases. Appears to regulate cell death by blocking the voltage-dependent anion channel (VDAC) by binding to it and preventing the release of the caspase activator, CYC1, from the mitochondrial membrane. Also acts as a regulator of G2 checkpoint and progression to cytokinesis during mitosis. Isoform Bcl-X(L) also regulates presynaptic plasticity, including neurotransmitter release and recovery, number of axonal mitochondria as well as size and number of synaptic vesicle clusters. During synaptic stimulation, increases ATP availability from mitochondria through regulation of mitochondrial membrane ATP synthase F(1)F(0) activity and regulates endocytic vesicle retrieval in hippocampal neurons through association with DMN1L and stimulation of its GTPase activity in synaptic vesicles. May attenuate inflammation impairing NLRP1-inflammasome activation, hence CASP1 activation and IL1B release. Isoform Bcl-X(S) promotes apoptosis.
Synonyms: BCL2L; BCLX; Bcl-X; bcl-xL; bcl-xS; PPP1R52; BCL-XL/S
Tractability: Small molecule: a drug acting on it is in phase 2 or 3 trials; a structure with a bound ligand is known; a high-quality ligand is known; it belongs to a druggable protein family. Antibody: UniProt predicts a signal peptide or a membrane-spanning region. PROTAC: it is named in the literature on targeted protein degradation; UniProt records ubiquitination sites on it; ubiquitination databases record sites on it; its protein half-life has been measured; a small molecule that binds it is known.
Target class: Ion channel; Other ion channel; Bcl-2 family; Miscellaneous ion channel
Chemical probes: A-1155463 (high quality), A-1211212 (high quality), A-1331852, DT2216 (high quality), NAVITOCLAX, PD082127, PD082281, PD083147, PD084736, PD085142, PD134257, PD134259, WEHI-539 (high quality)
Gene: Protein-coding gene on chromosome 20 (31,664,452 to 31,723,989, reverse strand). Ensembl gene ENSG00000171552.
Subcellular location: Mitochondrion inner membrane (Isoform Bcl-X(L)); Mitochondrion outer membrane; Mitochondrion matrix; Cytoplasmic vesicle, secretory vesicle, synaptic vesicle membrane; Cytoplasm, cytosol; Cytoplasm, cytoskeleton, microtubule organizing center, centrosome; Nucleus membrane
Subcellular location (Human Protein Atlas): Mitochondria; Acrosome; Nucleoli fibrillar center
Pathways (Reactome):
Disease: SARS-CoV-1-mediated effects on programmed cell death; STAT5 activation downstream of FLT3 ITD mutants
Immune System: Interleukin-4 and Interleukin-13 signaling; The NLRP1 inflammasome
Cellular responses to stimuli: NFE2L2 regulating tumorigenic genes
Programmed Cell Death: BH3-only proteins associate with and inactivate anti-apoptotic BCL-2 members
Signal Transduction: RAS processing
Gene Ontology:
Molecular function: BH3 domain binding; identical protein binding; protein binding; protein kinase binding; channel activity
Biological process: defense response to virus; negative regulation of apoptotic process; negative regulation of endoplasmic reticulum stress-induced intrinsic apoptotic signaling pathway; negative regulation of execution phase of apoptosis; negative regulation of extrinsic apoptotic signaling pathway via death domain receptors; negative regulation of intrinsic apoptotic signaling pathway; negative regulation of intrinsic apoptotic signaling pathway in response to DNA damage; negative regulation of protein localization to plasma membrane; regulation of cytokinesis; regulation of mitochondrial membrane permeability; regulation of mitochondrial membrane potential; release of cytochrome c from mitochondria; response to cytokine; apoptotic mitochondrial changes; extrinsic apoptotic signaling pathway in absence of ligand; intrinsic apoptotic signaling pathway in response to DNA damage; negative regulation of extrinsic apoptotic signaling pathway in absence of ligand; negative regulation of release of cytochrome c from mitochondria; positive regulation of apoptotic process; programmed cell death; regulation of apoptotic process; regulation of apoptotic signaling pathway; regulation of intracellular signal transduction; response to other organism; response to stress; and 1 more
Cellular component: Bcl-2 family protein complex; centrosome; cytoplasm; mitochondrion; cytosol; mitochondrial outer membrane; endoplasmic reticulum; membrane; mitochondrial inner membrane; mitochondrial matrix; mitochondrial membrane; nuclear membrane; synaptic vesicle membrane
Genetic constraint (gnomAD): Loss-of-function variants: 1 observed, 18.18 expected, observed/expected ratio (o/e) 0.055, 90% interval 0.019 to 0.26. The upper end of that interval is the gene's LOEUF score, 0.26, which puts it in group 1 of 6, group 1 being the genes least tolerant of losing a copy. Missense variants: 207 observed, 313.37 expected, observed/expected ratio (o/e) 0.66, 90% interval 0.59 to 0.74. Synonymous variants: 103 observed, 127.39 expected, observed/expected ratio (o/e) 0.81, 90% interval 0.69 to 0.95.
Homologues: Orthologues: chimpanzee BCL2L1 (100% identical), dog BCL2L1 (100% identical), macaque BCL2L1 (99% identical), pig BCL2L1 (98% identical), mouse Bcl2l1 (98% identical), rabbit BCL2L1 (97% identical), guinea pig BCL2L1 (96% identical), rat AC098008.1 (70% identical), zebrafish bcl2l1 (52% identical), tropical clawed frog bcl2l1 (48% identical). Paralogues in human: BCL2 (43% identical), BCL2L2 (40% identical), BAK1 (20% identical), MCL1 (20% identical), BOK (18% identical), BAX (18% identical), BCL2A1 (18% identical), BCL2L10 (15% identical).
Diseases named in the same sentence as BCL2L1 in open-access papers:
BCL2L1 is named in the same sentence as 383 diseases in open-access papers, as found by Europe PMC text mining. Sharing a sentence is not in itself a finding about the gene and the disease. The quoted sentences say what the papers report.
breast carcinoma (269 papers, 2002 to 2025). "BCL2L1, encoding two specific isoforms (Bcl-xL or Bcl-xS), has been shown to have functional roles in multiple cancer types, including breast cancer." (PMID 32101536, 2020). "Moreover, the BCL2L1 pre-mRNA is associated with greater tumor cell survival in various cancer types including human lymphoma, breast cancer, prostate cancer, and human hepatocellular carcinoma." (PMID 33649373, 2021). "Interestingly, breast cancer patients harboring nonsynonymous somatic mutations on BCL2L1-HRAS reveals poor survival rate compared to the wild-type status on both BCL2L1 and HRAS (P = 0, log-rank test)." (PMID 32101536, 2020). "In further support of its tumor suppressor function, RBM25 was previously found to be mutated in breast cancer and to favor the expression of the pro-apoptotic isoform of the BCL2L1 pre-mRNA, the latter via its role in 5ʹ splice site selection in the context of the U1 snRNP20,43,44." (PMID 30635567, 2019). "Together, these data suggest that loss or inhibition of BCL2L1 may be useful in combination with TRAIL in a broad spectrum of breast cancer subtypes." (PMID 24745479, 2014). "BCL2L1 inhibition combined with RT dramatically impeded tumor growth in several breast cancer cell lines and syngeneic models." (PMID 38316463, 2024). "We have recently demonstrated that in breast cancer, this “apoptosis-resistance” is underpinned in part by activation of a super-enhancer spanning the BCL2L1 locus, which increases intracellular levels of the anti-apoptotic Bcl-2 family protein Bcl-xL." (PMID 35248122, 2022). "The lncRNA GSN-AS1 (ENSG00000235865) regulates BCL2L1, which has been proven to be an important prognostic marker for luminal subtype breast cancer." (PMID 34079798, 2021). "Aripiprazole also increased the expression of certain pro-apoptotic genes (caspases 3, and BCL10), while expression of anti-apoptotic genes (BCL2L1, and c-myc) that are involved in the progression of breast cancer were decreased." (PMID 32746451, 2020). "Among the novel breast cancer oncogenes identified in this study was the anti-apoptotic protein BCL2L1." (PMID 27153554, 2016). "Our observation is in agreement with reports of CDK9i suppressing BCL2L1 expression in breast cancer cells." (PMID 26812885, 2016). "Taken together, these results suggest that functional oncogene signatures can accurately predict drug sensitivity and specifically support a role for BCL2L1 as a novel driver oncogene and potential therapeutic target in a subset of breast cancers." (PMID 27153554, 2016). "Data from the TCGA database indicates that a significant portion of breast cancers harbor amplification and/or overexpression of BCL2L1." (PMID 27153554, 2016). "We also identified an additional breast cancer cell line with amplification and over-expression of BCL2L1 and showed that this cell line was similarly sensitive to BCL2L1 inhibition." (PMID 27153554, 2016). "ZNF217 induced overexpression of both the Bcl-XL and Aurora-A proteins in paclitaxel-resistant ZNF217-overexpressing breast cancer cells, and expression of BCL2L1 protein correlated with that of ZNF217 mRNA in colorectal tumors." (PMID 26431164, 2015). "Expanded screening of five BCL2L1 siRNAs confirmed that BCL2L1 LOF results in enhanced TRAIL activity in four breast cancer cell lines." (PMID 24745479, 2014). "These authors also showed that co-culture of human MDA-MB-231 breast cancer cells with murine astrocytes protected the cancer cells from apoptosis by vincristine through upregulation of the anti-apoptotic survival genes, BCL2L1, TWIST1, and GSTA5." (PMID 25566497, 2014). "Moreover, MCPIP1 expression has been shown to act as a potent tumor suppressor in breast cancer cells by inducing tumor apoptosis through selectively suppressing the expression of antiapoptotic gene transcripts, including Bcl2L1 and Bcl2A1." (PMID 39815326, 2025).
breast carcinoma (continued). "Taken together, our results suggest that the combination of an apoptosis inhibitor such as a BCL2L1 inhibitor with RT may represent a promising anticancer strategy for solid cancers including breast cancer." (PMID 38316463, 2024). "The role of Bcl2-L1 in breast cancer is yet to be investigated." (PMID 37736508, 2023). "Furthermore, MCL1 expression and amplification exceeded that of BCL2 and BCL2L1 (Bcl-xL) in clinical ER+ breast cancer samples." (PMID 35053443, 2022). "Possible mechanisms of resistance to BETis encompass AMPK-ULK1-mediated autophagy in AML, NF-κB in colorectal cancer, PP2A phosphatase and BCL2L1/BCL-X in breast cancer, the GLI2-dependent Hedgehog pathway in pancreatic cancer and kinome reprogramming in ovarian cancer, among others." (PMID 34681760, 2021). "The open peaks around the promoter region of BCL2L1 gene locus showed ubiquitous accessibility; however, the distal regulatory region of the BCL2L1 gene locus showed variable accessibility across gynaecologic and breast cancers." (PMID 32419250, 2020). "Importantly, this study demonstrates that phenocopying SRC and BCL2L1 LOF by pharmacologic inhibition can sensitize TRAIL-resistant breast cancer cell lines to TRAIL-induced apoptosis." (PMID 24745479, 2014). "Based on our siRNA studies, the LOF of SRC may potentially represent a context-specific modulator of TRAIL activity, whereas LOF of BCL2L1 may modulate TRAIL activity in a broader range of breast cancer cell types." (PMID 24745479, 2014). "Thus, targeting BCL2L1-HRAS by APG-1252 may offer potential therapeutic strategies for treatment of KRAS mutant breast cancer." (PMID 32101536, 2020). "A model can be proposed whereby ZNF217 cooperates with Aurora-A, BCL2L1 or eEF1A2 in neoplastic progression of breast cancer through genomic co-amplification and/or through ZNF217-driven molecular regulation, which might amplify the impact of any genomic amplification." (PMID 26431164, 2015). "Further validating this finding in a panel of breast cancer cell lines, we confirmed that BRD-810 sensitivity strongly correlated with the BCL2L1:BAK expression ratio using mRNA or protein quantification." (PMID 39179926, 2024). "The induction of antiapoptotic genes, including B-cell CLL/lymphoma 2 (BCL2), BCL2 related protein A1 (BCL2A1), BCL2 like 1 (BCL2L1), BCL2L2, and myeloid cell leukemia 1 (MCL1), has been observed in multiple cancers, including breast cancer." (PMID 36853387, 2023). "To further investigate the implications of overexpression of Aurora A and Bcl-xL in TNBC breast cancer patients, we assessed the correlation between AURKA and BCL2L1 mRNA expression and clinical outcomes using the web-based tool KM plotter." (PMID 36077449, 2022). "MDM2 ligase, coupled with inhibitors of the targets BCL2L1, BRD4, CDK9, PLK1 and MCL1 in stomach cancer, and MDM2 with PIK3C3 inhibitors in breast cancer seemed to be the best therapeutic construction." (PMID 35249548, 2022). "Both arsenic compounds upregulate expression levels of antiapoptotic genes BCL2 and BCL2L1 and downregulate expression levels of proapoptotic genes CASP8 and CASP9, promoting apoptosis in breast cancer cells." (PMID 36619302, 2022). "The drug was also able to significantly increase the nuclear condensation, and modulated the expression of certain genes involved in breast cancer, such as caspases 3, and 9, BAK-1, C-MYC, BCL2L1, BCL-10, and BCL-2." (PMID 32746451, 2020). "Here, we identified several statistically significant genetic interactions (e.g., BCL2L1 [P = 5.65x10-3], S6B Fig) for HRAS in breast cancer." (PMID 32101536, 2020). "Our data suggest that, in breast cancer cells, YAP1/β-catenin complex with TBX3, which phenocopies TBX5 at BCL2L1 and BIRC5 but additionally promotes cMYC expression, potentially by combining known TEAD- and TBX3-binding elements." (PMID 26549256, 2015).
breast carcinoma (continued). "Further, we confirmed that small-molecule inhibition of SRC or BCL2L1, in combination with TRAIL, sensitizes breast cancer cells to TRAIL-induced apoptosis, including cell lines resistant to TRAIL-induced cytotoxicity." (PMID 24745479, 2014). "Overall, this suggests that BCL2L1, BIRC2, and ACTN4 are potentially major regulators of TRAIL-induced caspase-3/7 in breast cancer and that their LOF has the potential to overcome resistance to TRAIL-induced cytotoxicity." (PMID 24745479, 2014). "ABT-737 is an inhibitor of BCL-XL (BCL2L1), BCL-w (BCL2L2), and BCL-2 that has been shown to enhance cell death, including in MCF7 breast cancer cells and myeloma cells by binding and inhibiting the activity of antiapoptotic BCL2 family members." (PMID 24745479, 2014). "Moreover, we uncovered BCL2 family proteins, including BCL2L1 and MCL1 as potential mechanisms for radiation resistance not only in MCF10A cells but also in multiple human and murine breast cancer cell lines." (PMID 38316463, 2024). "The five antiapoptotic genes (BCL2, BCL2A1, BCL2L1, BCL2L2, and MCL1) are frequently overexpressed in ER-positive breast cancer cells, and these genes have been used as clinical biomarkers in the diagnosis of breast cancer." (PMID 36853387, 2023). "In our study, untreated breast cancer cell lines were shown to express high amounts of Bcl2-L1, whereas cell lines treated with the test compounds showed no expression of Bcl2-L1." (PMID 37736508, 2023). "Here, we revealed that BCL2, BCL2A1, BCL2L2, and MCL1 but not BCL2L1 were overexpressed in estrogen receptor (ER)-positive breast cancer cells and clinical biopsies." (PMID 36853387, 2023). "This is in line with the analysis of breast cancer cell lines in Cancer Cell Line Encyclopedia data, which highlights a role for both MCL1 and BCL2L1 (BCL-XL) in maintenance of breast cancer cell line viability in 2-D culture, whereas BCL2 appears largely non-essential in this context." (PMID 35349392, 2022). "High levels of Bcl-xL or Aurora A have been previously correlated with poor overall survival (OS) and short progression-free survival (PFS) in breast cancer, including TNBC, but a correlation between co-expression of AURKA and BCL2L1 and TNBC patient survival has not yet been reported." (PMID 36077449, 2022). "In this study, we identified BCL2L1 (BCL-XL) as a key node in determining sensitivity and further showed that inhibition of the BCL-2 family by the small-molecule inhibitor, ABT-737, enhances TRAIL-induced toxicity in breast cancer cell lines." (PMID 24745479, 2014). "Interestingly, both BCL-XL (BCL2L1) and BCL-w (BCL2L2) were identified as negative regulators of TRAIL-induced caspase-3/7 activation in the breast cancer cells by our primary screen." (PMID 24745479, 2014). "This set comprised senescence markers (CDKN1A, LMNB1, MKI67), apoptosis regulators (BCL2, BCL2L1), a highly overexpressed gene (ITGB6), and drug targets (ACTA2, GSDMC, KRT6A, PDE1A, PSMA8), all of which showed strong concordance with our RNA-seq data in all four breast cancer cell lines." (PMID 40312750, 2025). "Furthermore, according The Cancer Genome Atlas (TCGA) genetic amplification of Bcl2 and Bcl2l1 (encoding Bcl-xL) occurs in less than 3% of luminal B and TNBC cases, implying that BH3-mimetic targeting of Bcl-2 and Bcl-xL may not be beneficial in most breast cancer subtypes." (PMID 25784482, 2015). "The BCL2L1 gene, which is part of the SUM-185 functional oncogene signature, was of particular interest because a role for amplified BCL2L1 as a driver oncogene in breast cancer has not been previously characterized." (PMID 27153554, 2016).
Thrombocytopenia (243 papers, 2011 to 2026). A reduction in the number of circulating thrombocytes. "Bcl-xL (Bcl2l1) is required for maintaining platelet survival in adult mice, and we have previously shown that tet-regulated Bcl-xL knockdown in megakaryocytes causes severe thrombocytopenia." (PMID 23326559, 2013). "We found eight proteins (ITGA2B, ITGB3, VWF, PLEK, TNF, TLR2, BCL2 and BCL2L1) were the core targets of DMAG for the treatment of thrombocytopenia." (PMID 34837956, 2021). "In a phase 1 study, the dual BCL2 and BCL2L1 (BCL-xL) inhibitor navitoclax demonstrated on-target activity, but with the off-tumor effect of thrombocytopenia." (PMID 37509251, 2023).